NUP153 (nucleoporin 153)
Diseases named in the same sentence as NUP153 in open-access papers (continued):
Sharing a sentence is not in itself a finding about the gene and the disease.
infection (continued). "Regarding infectivity, silencing of LEDGF decreased infection to a greater extent than silencing of ADAM10 or Nup153." (PMID 23028330, 2012). "Since efficient knock-down was already possible at 2 days post-infection, we chose to use all Nup153 knock-downs at this point comparing them with the corresponding control." (PMID 23049930, 2012). "When cells were treated with Cs during infection, infectivity reduced by Nup153 depletion was specifically rescued for wild type virus, whereas the HIV-1 CA mutants remained unaffected." (PMID 22174692, 2011). "Later during infection, other Nups have been reported to be targeted as well by both 2Apro (Nup62, Nup153, and Nup358), and by 3Cpro (Nup153, Nup214, and Nup358), but the extent to which these contribute to the NCTD is unknown." (PMID 40875754, 2025). "At 16 h post-infection, the cells were fixed and subjected to U-ExM and indirect immunostaining using two different antisera against CA, along with immunostaining against Nup153 and BODIPY staining." (PMID 39459943, 2024). "Moreover, infection by these mutants was minimally affected by depletion of the nucleoporin Nup153, which reduces infection by wild type HIV-1." (PMID 39259747, 2024). "In contrast, EIAV has an appreciable ability to interact with NUP153 and utilizes it for infection." (PMID 34702294, 2021). "In conclusion, we hypothesise that during a productive infection, a capsid remodelling step takes place at the nuclear pore that releases the core complex from Nup153, and relays it to CPSF6, which then localises it to chromatin ready for integration." (PMID 34543344, 2021). "Furthermore, transportin-3 (TNPO3) and the nuclear pore complex component nucleoporin 153 (NUP153) were shown to be important for infection by HIV-1." (PMID 31652959, 2019). "However, while HIV-1N57S infection was indeed largely insensitive to NUP153 depletion in HOS and HT1080 cells, HIV-1WT and HIV-1N57S were equivalently sensitive to NUP153 knockdown in HeLa cells." (PMID 30084827, 2018). "This opposite effect on SIVmnd1 infection as compared to the Nup358/RanBP2 knockdown suggested that Nup153 may interfere with the engagement of another nucleoporin preferentially recruited by some of the circulating SIV." (PMID 23883001, 2013). "Microarray analysis of mock and HSV-1-infected primary rat embryonic fibroblast reveals that HSV-1 decreases Nup153 gene expression by greater than 3-fold, while immunofluorescence of HSV-1-infected cells indicates that Nup153 is dislocated to the cytoplasm at early times post-infection." (PMID 23959328, 2013). "Accordingly, alterations in the rate or extent of CA core uncoating may alter engagement of NUP153 during infection." (PMID 24130490, 2013). "Moreover, Nup153 depletion slightly inhibited infection by SIVmac (ratio 0.5; p < 0.05) and SIVmon (ratio 0.7; p < 0.05), with either no significant inhibitory effect on the other circulating SIV or even a significantly increased infection as observed for SIVmnd1 (ratio 1.5; p < 0.05)." (PMID 23883001, 2013). "Alternatively, disrupting the ability of the capsid to interact with FG-containing cofactors (Sec24C, Nup153, and CPSF6) has also been proposed to inhibit infection." (PMID 38347802, 2024). "Whereas CsA treatment, predictably, does little to affect P90A infection in the POM121 or Nup153 knockdown cells, CPSF6 depletion potently enhances infection when in conjunction with either knockdown." (PMID 37355754, 2023). "First, the 5Mut virus lost the ability to interact with CPSF6 and CypA and became less dependent on NUP153 and NUP358 for infection." (PMID 34702294, 2021). "Mutations in HIV-1 CA had variously altered effects of NUP153 depletion on infection; most strikingly, HIV-1G89V infection was unaffected by NUP153 depletion." (PMID 30084827, 2018).
infection (continued). "The CsA dependence of HIV-1A92E infection in HeLa cells was exaggerated by some Nup knockdowns (e.g. NUP93, NUP205, NUP54, NUP153) while other knockdowns reduced or eliminated the enhancing effects of CsA (e.g. NUP98, NUP107, NUP155)." (PMID 30084827, 2018). "Three days after transduction of HeLa P4-CCR5 at the indicated multiplicities of infection (MOI), expression of Nup153 and Tpr was monitored by western blotting." (PMID 25744187, 2015). "In conclusion, we show for the first time that 3C protease mediates cleavage of Nup153 and effects the mislocalisation of SC35 and nucleolin observed in HRV16 infection." (PMID 23951130, 2013). "Curiously, although HIV-1 appears to rely upon NUP358, NUP153, TNPO3, and CPSF6 during infection, other lentiviruses only appear to share certain aspects of this mechanism." (PMID 24103892, 2013). "Notably, 9 nucleoporins (NUP58, NUP214, NUP98, NUP54, NUP62, NUP88, NUP153, POM121/NUP121 and RANBP2/NUP358) and the mRNA export factor Rae1 were present in both the CebN infection and transfection interactomes." (PMID 38712050, 2024). "Nonetheless, the effect(s) of NUP153 and CPSF6 binding to CA on capsid stability remain ambiguous; thus, it remains to be determined which host factor(s), if any, regulate HIV-1 capsid stability during infection." (PMID 34613803, 2021). "Namely, infection of the N74D mutant is insensitive to depletion of NUP358 and NUP153." (PMID 34702294, 2021). "As such, the fold rescue of infection, measured as the ratio between infection levels in the presence or absence of CsA, was higher in Nup153 KD cells compared to DsRed KD T5Cyp cells." (PMID 27107820, 2016). "Furthermore, capsid was found to be responsible for the viral requirement of various nuclear transport proteins, including transportin 3 and nucleoporins NUP153 and NUP358, during infection." (PMID 24103892, 2013). "The correlation however was not absolute, as N74D, G89V, P90A, and T107N mutant viruses did not require NUP153 for infection yet remained cell cycle independent." (PMID 24130490, 2013). "Nonetheless, we observed that Nup358/RanBP2 and Nup153 are not required for efficient infection by circulating SIV isolates and that the direct binding of Nup358/RanBP2 via its Cyp-like domain does not seem necessary." (PMID 23883001, 2013). "Co-silencing of LEDGF with ADAM10 resulted in a slightly more robust reduction of infection than with Nup153, but both combinations were more efficient than silencing LEDGF alone, and co-silencing of ADAM10 and Nup153 also resulted in lower infectivity than silencing of each one individually." (PMID 23028330, 2012). "However, NUP153 requirement for infection is not conserved among primate lentiviruses, as the sensitivity of NUP153 depletion drastically vary among circulating SIV strains." (PMID 34702294, 2021). "However, NUP153 binding is not correlated with NUP153 dependence for infection, as the N74D mutant, which is independent from NUP153, displays hyper-binding activity to NUP153." (PMID 34702294, 2021). "Next, we challenged Nup153 and Tpr-depleted cells with HIV-1ΔEnv pseudotyped with vesicular stomatitis virus G protein (VSV-G) expressing the luciferase (Luc; HIV-1-Luc) or RFP (HIV-1-RFP) measured 48 h post infection (p.i.)by luminescence assay or flow cytometry." (PMID 25744187, 2015). "Regardless if Nup153 has a direct or indirect effect on core stability, we might need to reconsider some of the early steps of the HIV-1 life cycle: it was assumed that HIV-1 uncoating starts early post-infection and is completed well before the PIC enters the nucleus." (PMID 27107820, 2016). "They noticed that two FG-nucleoporins, NUP153 and NUP62, were no longer detectable by western blot after 4.5 h of infection, a timing that correlated with nucleocytoplasmic trafficking perturbation." (PMID 34201715, 2021). "We observed that infection by CA mutants restricted by CPSF6 is less dependent or independent of the nucleoporins RanBP2 and Nup153." (PMID 24415937, 2014).
infection (continued). "Indeed, with the notable exceptions of RANBP2 and NUP153, Nup depletions generally had a smaller effect on HIV-1WT infection in non-dividing as compared to dividing HeLa cells." (PMID 30084827, 2018). "Similarly, CA mutant virus N57A is NUP153 and CPSF6 binding-defective, detectably binds the NUP358 CHD, yet does not require NUP358 expression for infection." (PMID 24130490, 2013). "Interestingly, the N74D mutant is defective for CPSF6358 binding but is competent to bind both NUP153 and NUP358, yet requires neither of these nucleoporins for infection." (PMID 24130490, 2013).
cancer (12 papers, 2010 to 2025). A tumor composed of atypical neoplastic, often pleomorphic cells that invade other tissues. "To further understand the relationship between NUP153 expression and cancer, we analysed NUP153 mutations in cancer." (PMID 40607419, 2025). "Based on the integrated analysis of the TCGA pan-cancer cohort and the TCGA-GTEx normal tissue database, we systematically evaluated the diagnostic efficacy of NUP153 as a cancer biomarker." (PMID 40607419, 2025). "In this study, we analysed the relationship between NUP153 and multiple cancers, including NUP153 expression, mutations, diagnostic value, prognostic significance, its relationship with cellular pathways, immune environment, and drug sensitivity." (PMID 40607419, 2025). "Pan-cancer analysis revealed that in most cancers, NUP153 expression was positively correlated with tumour-associated macrophage (TAM) infiltration levels." (PMID 40607419, 2025). "NUPs, including Nup153, appear to be implicated in a large number of disorders, such as cardiomyopathy associated to muscular dystrophy, autoimmune disease and cancer." (PMID 29963256, 2018). "However, the role of NUP153 in cancer, especially its expression patterns, mutations, diagnostic value, and relationship with the tumour immune microenvironment, remains insufficiently explored." (PMID 40607419, 2025). "However, additional studies are required to elucidate the specific molecular mechanisms underlying NUP153’s function in cancer and to explore its clinical applicability." (PMID 40607419, 2025). "Moreover, a previous study revealed that enhancer-specific chromatin structure and organization regulation by mammalian NUP153 is another underlying mechanism of cancer." (PMID 39080077, 2024). "Our results showing that Nup153 positively regulates cell migration and is associated with aberrant nuclear structure in PCa is in line with previous findings describing the role of this nucleoporin in nuclear shaping and cell motility in other cancers." (PMID 29963256, 2018). "Thus, we propose that enhancer-specific regulation of chromatin structure and organization by mammalian NUP153 may apply to other FG-Nups and contribute to the gene regulatory mechanisms that underlie FG-Nup fusion protein-associated cancers." (PMID 32451376, 2020). "Our study further suggests that NUP153 tends to exhibit strong immunoreactivity in the nucleus and nuclear membrane across a range of cancers." (PMID 40607419, 2025). "By identifying its potential oncogenic and tumour-suppressive roles, we not only expand the understanding of NUP153 beyond virology and basic cell biology, but also highlight its value as a novel focus for cancer research." (PMID 40607419, 2025). "In some cancer types, NUP153 expression is positively correlated with immune gene expression, while in others, it is negatively correlated." (PMID 40607419, 2025). "Through multi-dimensional analysis of unpaired tumour samples and paired tumour-normal samples from the TCGA database, we systematically analysed the expression profile of NUP153 in 33 types of cancer and physiological states." (PMID 40607419, 2025). "To gain a broader understanding of its role in cancer, we first analysed the expression pattern of NUP153 across multiple cancer types and normal tissues." (PMID 40607419, 2025). "The organ-specific expression map showed that NUP153 levels were relatively low in the liver and stomach under normal conditions, but markedly elevated in the brain, oesophagus, and stomach in cancer tissues." (PMID 40607419, 2025). "Given its significant correlations with patient prognosis across multiple cancer types, NUP153 holds potential as a clinically relevant biomarker." (PMID 40607419, 2025). "In conclusion, this study systematically explored the expression patterns and functional roles of NUP153 across various cancers through multi-omics analysis and experimental validation." (PMID 40607419, 2025).
cancer (continued). "In contrast, our study provides new insight into the cancer-specific genetic alterations of NUP153 and their functional consequences." (PMID 40607419, 2025). "NUP153 is aberrantly expressed in various cancers, including CRC, HCC, BC (Zhou and Panté 2010), PCa, and thyroid cancer." (PMID 39080077, 2024). "Of note, Nup153 knockdown was responsible for the alteration of nuclear lamin A in these cancer cells." (PMID 29963256, 2018). "The high frequency of mutations in NUP153 in UCEC suggests that it may be closely related to the development and progression of this cancer." (PMID 40607419, 2025). "This study also revealed a significant correlation between NUP153 expression and cancer prognosis." (PMID 40607419, 2025). "This suggested that the expression pattern of NUP153 could potentially serve as a predictor of sensitivity to cancer immunotherapy." (PMID 40607419, 2025). "However, the precise molecular mechanisms of NUP153 in cancer remain to be further investigated to support its clinical application." (PMID 40607419, 2025). "Importantly, this experimental evidence complements the bioinformatic and pan-cancer analyses conducted earlier in our study, strengthening the link between NUP153 overexpression and malignant phenotypes." (PMID 40607419, 2025). "In addition, our study highlighted that NUP153 expression showed heterogeneous immune infiltration characteristics across different cancers." (PMID 40607419, 2025). "These genetic alterations likely affect NUP153’s functional role in tumour progression and may account for its varied expression across cancer types." (PMID 40607419, 2025). "By identifying agents capable of downregulating NUP153, our study provides a promising therapeutic direction for tumours with high NUP153 expression, and lays the groundwork for future clinical investigations into pan-cancer therapies based on NUP153 inhibition." (PMID 40607419, 2025). "This study focuses on investigating the relationship between NUP153 expression levels and cancer." (PMID 40607419, 2025). "Additionally, reduction in expression of nucleoporin 153 by siRNA targeting reduced ERK1/2 nuclear activity in cancer cells." (PMID 20174585, 2010). "However, there is limited research on the relationship between NUP153 and cancer." (PMID 40607419, 2025). "Moreover, our analysis also showed that NUP153 expression is negatively correlated with the sensitivity to most chemotherapy drugs in the GDSC database, suggesting that high NUP153 expression may reduce cancer cell sensitivity to chemotherapy drugs." (PMID 40607419, 2025). "Therefore, targeting the inhibition of NUP153 expression may serve as a potential strategy based on computational evidence to enhance chemotherapy sensitivity in cancer cells." (PMID 40607419, 2025). "Thus, we first investigated by Co-IP the potential Nup153 interaction with the HAT member p300 and found that E2 treatment strongly enhanced their association in PCa cells compared to un-stimulated and estrogen-deprived cancer cells." (PMID 29963256, 2018). "Finally, biological experiments disclosed that NUP153 and USB1 can significantly impact cancer cell proliferation and migration." (PMID 33816259, 2021). "Further analysis of diagnostic performance curves showed a significant correlation between NUP153 expression levels and the sensitivity and specificity in distinguishing cancer from non-cancer samples, supporting its potential as an auxiliary diagnostic biomarker." (PMID 40607419, 2025).